APH1A (aph-1A gamma-secretase subunit)
Description:
Non-catalytic subunit of the gamma-secretase complex, an endoprotease complex that catalyzes the intramembrane cleavage of integral membrane proteins such as Notch receptors and APP (amyloid-beta precursor protein). Required for normal gamma-secretase assembly. The gamma-secretase complex plays a role in Notch and Wnt signaling cascades and regulation of downstream processes via its role in processing key regulatory proteins, and by regulating cytosolic CTNNB1 levels (Probable).
Synonyms: APH-1a; CGI-78; 6530402N02Rik; APH-1
Tractability: Small molecule: a drug acting on it is in phase 2 or 3 trials; a structure with a bound ligand is known; a high-quality ligand is known; it belongs to a druggable protein family. Antibody: its Gene Ontology location is reachable by antibodies, with high confidence; UniProt predicts a signal peptide or a membrane-spanning region. PROTAC: ubiquitination databases record sites on it; its protein half-life has been measured; a small molecule that binds it is known.
Gene: Protein-coding gene on chromosome 1 (150,265,399 to 150,269,580, reverse strand). Ensembl gene ENSG00000117362.
Subcellular location: Endoplasmic reticulum membrane; Golgi apparatus, Golgi stack membrane
Pathways (Reactome):
Signal Transduction: Activated NOTCH1 Transmits Signal to the Nucleus; NOTCH2 Activation and Transmission of Signal to the Nucleus; NOTCH3 Activation and Transmission of Signal to the Nucleus; NOTCH4 Activation and Transmission of Signal to the Nucleus; NRIF signals cell death from the nucleus; Noncanonical activation of NOTCH3; Nuclear signaling by ERBB4; Regulated proteolysis of p75NTR; TGFBR3 PTM regulation
Disease: Constitutive Signaling by NOTCH1 HD+PEST Domain Mutants; Constitutive Signaling by NOTCH1 PEST Domain Mutants
Developmental Biology: EPH-ephrin mediated repulsion of cells
Metabolism of proteins: Amyloid fiber formation
Gene Ontology:
Molecular function: endopeptidase activator activity; protein binding; protein-macromolecule adaptor activity; enzyme binding
Biological process: amyloid precursor protein catabolic process; amyloid precursor protein metabolic process; amyloid-beta formation; membrane protein ectodomain proteolysis; membrane protein intracellular domain proteolysis; Notch receptor processing; protein processing; Notch signaling pathway; proteolysis
Cellular component: endoplasmic reticulum; endoplasmic reticulum membrane; gamma-secretase complex; Golgi apparatus; membrane; plasma membrane; endosome membrane; Golgi membrane; Golgi cisterna membrane
Genetic constraint (gnomAD): Loss-of-function variants: 16 observed, 30.16 expected, observed/expected ratio (o/e) 0.53, 90% interval 0.36 to 0.81. The upper end of that interval is the gene's LOEUF score, 0.81, which puts it in group 3 of 6, group 1 being the genes least tolerant of losing a copy. Missense variants: 245 observed, 350.96 expected, observed/expected ratio (o/e) 0.7, 90% interval 0.63 to 0.78. Synonymous variants: 144 observed, 145.99 expected, observed/expected ratio (o/e) 0.99, 90% interval 0.86 to 1.13.
Homologues: Orthologues: chimpanzee APH1A (100% identical), rabbit APH1A (99% identical), dog APH1A (99% identical), guinea pig APH1A (99% identical), mouse Aph1a (99% identical), rat Aph1a (99% identical), pig APH1A (92% identical), macaque APH1A (81% identical), tropical clawed frog aph1a (73% identical), Drosophila melanogaster aph-1 (43% identical), Caenorhabditis elegans aph-1 (29% identical). Paralogues in human: APH1B (55% identical).
Diseases named in the same sentence as APH1A in open-access papers:
APH1A is named in the same sentence as 23 diseases in open-access papers, as found by Europe PMC text mining. Sharing a sentence is not in itself a finding about the gene and the disease. The quoted sentences say what the papers report.
Alzheimer disease (7 papers, 2010 to 2024). A progressive, neurodegenerative disease characterized by loss of function and death of nerve cells in several areas of the brain leading to loss of cognitive function such as memory and language. "We speculate that SNPs in the Aph1a coding region may affect the accumulation of Aβ and may have causative or protective effects in Alzheimer’s disease." (PMID 35008932, 2022). "In addition, SNPs in a promoter region of the Aph1a gene was associated with risk for developing sporadic Alzheimer’s disease in a Chinese population." (PMID 35008932, 2022). "Mapping the Alzheimer’s disease pathway onto the network resulted in the recovery of all the proteins and their corresponding interactions in the pathway except for APH1A." (PMID 23885764, 2013).
breast carcinoma (5 papers, 2013 to 2025). "APH1A, a component of the γ-secretase complex, was found to be a druggable cancer driver associated with high expression in endometrial and breast cancers." (PMID 36230806, 2022). "It is reported that increased expression of APH1A underlies endocrine therapy resistance in breast cancer." (PMID 36230806, 2022). "Low APH1A expression has been linked to a higher risk of breast cancer-specific death." (PMID 36476410, 2022). "There was a significant association between the low expression levels of PS1, Aph1a, Aph1b, and NCT and poor breast cancer specific survival." (PMID 24223915, 2013). "An AS event on APH1A has been identified a predictor in breast cancer." (PMID 36694725, 2023). "For example, we found an APA event on HNRNPA1 in breast cancer (apa_event_4540), and it may potentially affect the AS event on APH1A." (PMID 36694725, 2023). "We found no preference for any of the subunit variants (PS1/PS2 and Aph1a/Aph1b) over the other in our sample set of breast cancer tissues." (PMID 24223915, 2013). "In conclusion, this is to our knowledge the first report describing mRNA expression levels of γ-secretase subunits PS1, PS2, Aph1a, Aph1b, PEN-2, and NCT in breast cancer tissues." (PMID 24223915, 2013).
pancreatic cancer (3 papers, 2018 to 2022). "APH1A is involved in tumorigenesis and progression and plays a role in the invasion of cervical and pancreatic cancer." (PMID 35692877, 2022). "We measured the expression of key members of the Notch Signaling Pathway (NUMB, DTX4, DTX3L, PSEN1, APH1A, ADAM17 and EP300) in the MiaPaCa-2-miR-148a by qRT-PCR, and compared it with the basal levels of the control pancreatic cancer cell line MiaPaCa-2, expressing very low levels of miR-148a." (PMID 29464088, 2018).
glioma (2 papers, 2019 to 2023). A benign or malignant brain and spinal cord tumor that arises from glial cells (astrocytes, oligodendrocytes, ependymal cells). "In high-grade gliomas, RYR2, MCHR2, FADS6, HTR2C, CMTM3, APH1A, and PFN1 genes are related to membrane function." (PMID 37239411, 2023).
triple-negative breast carcinoma (2 papers, 2013 to 2016). An invasive breast carcinoma which is negative for expression of estrogen receptor (ER), progesterone receptor (PR), and human epidermal growth factor receptor 2 (HER2). "It is relevant that 9 tumors have a deletion of two genes previously related to cancer progression such as PLEKHO1 a negative regulator of the mitogenic PI3K/AKT signaling pathway and APH1A which loss of expression has been associated to poor survival in triple negative breast cancer patients." (PMID 26979459, 2016).
asthma (1 paper, 2023). "The top 20 genes including the PTBP1, RAB11FIP3, APH1A, and MYD88 were recognized as the most frequent items among severe asthma association rules." (PMID 37717070, 2023).
endometrial cancer (1 paper, 2022). Primary or metastatic malignant neoplasm involving the endometrium (mucous membrane that lines the endometrial cavity). "The Human Protein Atlas and our preliminary data demonstrated that high expression of APH1A, GDH2, SETDB1, and SOX9 are associated with low survival in endometrial cancer." (PMID 36230806, 2022).
familial Alzheimer disease (1 paper, 2009). A degenerative disease of the brain that causes gradual loss of memory, judgment, and the ability to function socially. "These manipulations include introducing familial Alzheimer's disease L166P PS1 mutation, structural change in the Pen2 N-terminus, expressing Aph1B or Aph1A isoform, or pharmacological treatment (fenofibrate, ibuprofen)." (PMID 19924286, 2009).
hepatocellular carcinoma (1 paper, 2022). A malignant tumor that arises from hepatocytes. "APH1A is highly expressed in grade-3 hepatocellular carcinoma (HCC)." (PMID 36217201, 2022).
lymphoma (1 paper, 2017). A malignant (clonal) proliferation of B- lymphocytes or T- lymphocytes which involves the lymph nodes, bone marrow and/or extranodal sites. "Thus, future studies should be directed to enhance our understanding of the function of APH1A isoforms and their relation to Notch signaling in DLBCL that may further improve opportunities for the design of selective lymphoma therapeutics." (PMID 28841210, 2017).
cancer (16 papers, 2013 to 2025). A tumor composed of atypical neoplastic, often pleomorphic cells that invade other tissues. "For example, both A1 and A2 identify gene APH1A as associated with all nine cancer types, but this gene is missed by A3." (PMID 31405076, 2019). "By analyzing interactions with the GNPDA1 protein using the STRING database, researchers identified 4 key genes (GABPB1, CDK4, ADNP, and APH1A) that play important roles in cellular processes related to cancer." (PMID 40419932, 2025). "The level of APH1A, CTBP1, HEY1, HEY2, JAG2, NOTCH4 was significantly higher in cancer samples compared to the control group, while the concentration of DTX1 TLE2, TLE4 was below the detection threshold." (PMID 41463075, 2025). "In addition, the proportion of the APH1A-203 and RABAC1-201 isoforms, which were upregulated in our data, exhibited a progressive increase across cancer stages in the TCGA cohort." (PMID 40702779, 2025). "Analysis revealed overexpression of APH1A, CTBP1, HEY1, HEY2, JAG2, NOTCH4 regardless of the cancer subtype." (PMID 41463075, 2025). "APH1A (anterior pharynx defective 1 homolog A) and NOTCH1, also found to be frequently upregulated genes in H class tumors, are components of the NOTCH signaling pathway, which when dysregulated, participates in a number of pathologies, including cancer and non-cancerous diseases." (PMID 35565454, 2022).
tumor (7 papers, 2008 to 2025). "Tumors expressing low amounts of APH1A had a high histological tumor grade, according to the findings." (PMID 36476410, 2022). "The list of genes with reduced expression in DA, as compared with increased expression in DA.F344(Cia5d) congenics, included seven genes that are involved in tumor suppression-like activity and cell cycle check-points, such as Aph1a, Brwd3, Gadd45b, Gmfg, Lox, and Plekhg2." (PMID 18706093, 2008). "Furthermore, overexpression of APH1A resulting from hypoxia in the tumor environment may ultimately promote growth and invasion, but more research is needed." (PMID 41463075, 2025). "Indeed, forced expression of miR-138–2 suppressed the tumor growth in vivo along with a significant down-regulation of NOTCH1, MAML1, APH1A and HES1." (PMID 36973704, 2023). "PSENEN and APH1A expression were correlated with tumor stage but not the tumor grade." (PMID 36476410, 2022).
infection (3 papers, 2019 to 2020). The state of being infected such as from the introduction of a foreign agent such as serum, vaccine, antigenic substance or organism. "The transcripts of APP, ADAM10, BACE1, and subunits of the γ-secretase complex (PSEN1, PSEN2 APH1A and NCSTN) were significantly upregulated (p < 0.05) in at least one of the 4 investigated timepoints post-infection." (PMID 30786875, 2019).
APH1A also shares sentences with these, for which no sentence is quoted: lung carcinoma (2 papers); aortic stenosis (1); breast tumors (1); cervical cancer (1); cryptococcosis (1); hidradenitis suppurativa (1); lobular carcinomas (1); melanoma (1); ovarian carcinoma (1); systemic lupus erythematosus (1).